RAB27A (RAB27A, member RAS oncogene family)
Diseases named in the same sentence as RAB27A in open-access papers (continued):
Sharing a sentence is not in itself a finding about the gene and the disease.
Immunodeficiency (11 papers, 2008 to 2024). Failure of the immune system to protect the body adequately from infection, due to the absence or insufficiency of some component process or substance. "In stark contrast to those of normal mice, in the background of immunodeficiency, the tumor growth rate and survival time of GL-261nSMase2−/−, Rab27a−/−, and LGALS9−/− tumor-bearing mice were not significantly different from those of GL-261WT tumor-bearing mice." (PMID 33093453, 2020).
pancreatic cancer (11 papers, 2016 to 2023). "Loss of Rab27a compromises efficient outgrowth of pancreatic cancer metastatic lesions, however, it also provides an advantage at the first steps of metastasis establishment, through upregulation of different genes associated with epithelial-to-mesenchymal transition." (PMID 37641131, 2023). "The Rab27a GTPase is overexpressed in advanced cancers, can regulate vesicle trafficking, and has been previously linked to non-cell autonomous control of tumor growth and metastasis, however, the role of Rab27a itself in the metastatic propensity of pancreatic cancer is not well understood." (PMID 32355248, 2020). "In this study, we aimed to address the role of Rab27a in modulating metastatic properties of pancreatic cancer in vivo." (PMID 32355248, 2020). "Downregulation of RAB27A/B attenuates proliferation/invasion and also leads to the enhanced efficacy of cisplatin with an induction of apoptosis in pancreatic cancer cells." (PMID 32756339, 2020). "Overall, these data reveal that Rab27a can play divergent roles in regulating pro-metastatic propensity of pancreatic cancer cells: by generating pro-metastatic environment at the distant organ sites, and by suppressing invasive properties of the cancer cells." (PMID 32355248, 2020). "In this study, we wanted to understand the role of Rab27a in facilitating the ability of pancreatic cancer cells to alter distant niches and/or to affect local tumor outgrowth." (PMID 32355248, 2020). "We, on the other hand, demonstrated that in pancreatic cancer, Rab27a has a role in facilitating systemic changes in immune milieu that are independent of its’ potential role in regulating primary tumor growth." (PMID 32355248, 2020). "Abnormal expression of Rab27a was found in colorectal and pancreatic cancers and was correlated with clinicopathological characteristics and clinical outcomes." (PMID 29725020, 2018). "Interestingly, a report on pancreatic cancer demonstrated for the first time a dual role for Rab27a in the metastatic potential of cancer cells." (PMID 37641131, 2023). "Rab27a is overexpressed in pancreatic cancer and predicts poor survival." (PMID 32355248, 2020). "Loss of Rab27a in pancreatic cancer cells did not decrease tumor growth in vivo, but resulted in altered systemic myeloid cell expansion, both in the primary tumors and at the distant organ sites." (PMID 32355248, 2020). "However, the role of Rab27a itself in the metastatic propensity of pancreatic cancer in vivo remains unclear." (PMID 32355248, 2020). "In addition to previously reported ability of primary pancreatic cancer to increase macrophage frequencies in livers, we report that Rab27a may also regulate different subtypes of myeloid cells in livers." (PMID 32355248, 2020). "In contrast, the expression of exosome-related proteins, such as RAB27A, TSG101 and CD9, increased immediately after radiation in pancreatic cancer cells." (PMID 32228703, 2020). "In addition, in pancreatic cancer unexpected extracellular surface expression of Plectin has recently been reported and this was shown to be necessary for exosome production in conjunction with proteins Rab27a and −b and required for sustaining tumor growth in immunocompetent mouse models." (PMID 27470985, 2016). "Overall this data suggests that slight in vitro modulation of cell growth by Rab27a in pancreatic cancer cells is not sufficient to alter in vivo growth rates." (PMID 32355248, 2020).
prostate carcinoma (9 papers, 2016 to 2024). A carcinoma that arises from epithelial cells of the prostate gland. "In a mouse model of prostate cancer which is resistant to anti-PD-L1 antibody, prostate cancer cells fail to grow in mice when Rab27A or aSNase2 was deleted." (PMID 38726017, 2024). "Tipifarnib, for instance, reduces exosome levels in prostate cancer cells by inhibiting RAB27A, Alix, and nSMase2." (PMID 39409917, 2024). "This was demonstrated by using a syngeneic model of prostate cancer with CRISPR/Cas9-mediated deletion of Rab27a and PD-L1 to reduce EV release and block PD-L1 protein expression, respectively." (PMID 39682778, 2024). "More importantly, the prostate cancer cells were also unable to grow in mice when Rab27a or aSNase2 was deleted by the CRISPR/Cas9 technique, leading to a blockade of exosome biogenesis." (PMID 33178688, 2020). "Meanwhile, Rab27a-deletion also increases the spleen size of mice injected with prostate cancer cells." (PMID 33178688, 2020). "Rab27A and Rab27B are frequently downregulated in advanced prostate cancer and are inversely correlated with prostate cancer outcomes." (PMID 30081925, 2018). "However, shRNA knockdown of Rab27a in a prostate cancer model revealed a dominant immunosuppressive role for EVs during antigen cross-presentation." (PMID 39008536, 2024). "Notably, intravenous injection of exogenous exosomes derived from WT prostate cancer cells resulted in decreased spleen size of mice injected with Rab27a-deleted prostate cancer cells to nearly 50%." (PMID 33178688, 2020). "Additionally, in the prostate cancer model, the mice injected with mutant cells deleted of PD-L1, Rab27a, or nSMase2 survived more than 90 days, whereas the mice injected with WT cells died soon or had to be euthanized because of tumors greater than 2 cm in diameter." (PMID 33178688, 2020). "In the TRAMP-C2 mouse prostate cancer model, mutant cancer cells devoid of Rab27a, nSMase2, or PD-L1 expression completely failed to grow." (PMID 33178688, 2020).
ovarian carcinoma (7 papers, 2019 to 2025). A malignant neoplasm originating from the surface ovarian epithelium. "Hypoxia activates the HIF signaling pathway, which contributes to enhanced EV release and increased Rab22A and Rab27a expression in breast and ovarian cancer cells." (PMID 40471522, 2025). "Increased Rab27a and decreased Rab7 levels increased exosome production in ovarian cancer cells under hypoxia." (PMID 39768002, 2024). "More recently, the relationship between miR-134-3p and Rab27a was validated in human ovarian cancer stem cells." (PMID 38326867, 2024). "Similarly, ovarian cancer cells exposed to hypoxia demonstrated enhanced EV production through the activation of Rab27a, suppression of Rab7, LAMP1/2, and NEU-1, and the induction of a more secretory lysosomal phenotype." (PMID 40471522, 2025). "The binding relationship between miR-134-5p and Rab27a has been reported on ovarian cancer cells; however, whether miR-134-5p can mediate Rab27a expression in osteoclasts remains to be determined." (PMID 38326867, 2024). "Recently, it has also been demonstrated that ovarian cancer cells in hypoxic conditions increased their exosome release by upregulating RAB27A and downregulating several protein among which RAB7A, and also by promoting a more secretory lysosomal phenotype with increased CDDP efflux." (PMID 30626032, 2019).
Chediak-Higashi syndrome (6 papers, 2016 to 2021). ChC)diak-Higashi syndrome (CHS) is a rare severe genetic disorder generally characterized by partial oculocutaneous albinism (OCA), severe immunodeficiency, mild bleeding, neurological dysfunction and lymphoproliferative disorder. "In addition, NGS did not reveal pathogenic/likely pathogenic variants in the genes associated with Griscelli syndrome type 1-3 (MYO5A, RAB27A, MLPH) or Chediak–Higashi syndrome (LYST)." (PMID 34685610, 2021). "Primary HLH can be caused by mutations in a number of genes which affect cytotoxic lymphocyte granule-mediated cytotoxicity including PRF1, UNC13D, STX11, STXBP2, RAB27A (Griscelli Syndrome), AP3B1 (Hermansky-Pudlak syndrome type 2), and LYST (Chediak-Higashi Syndrome)." (PMID 31396234, 2019).
viral infection (6 papers, 2021 to 2025). "IFN-γ was similarly implicated in models of HLH triggered by viral infection in mice mutated in perforin, Rab27a or Unc13d41–44." (PMID 34620855, 2021). "More importantly, viral infection upregulates the expression of Rab5 or Rab27a, thereby activating the formation of exosomes for delivery of viral particles to the salivary cavities." (PMID 34214032, 2021). "Viral infection induced a significant increase in the average number of Rab27a- or CD63-specific punctate structures in type III cells." (PMID 34214032, 2021). "In addition, functional enrichment analysis of genes with RNA editing highlighted that the Rab GTPase family played a common and vital role in the host immune response to IBP and ssRNA viral infections, which was indicated by the consistent up-regulated RNA editing of Ras-related protein Rab27a." (PMID 37081881, 2023). "Consistently, up-regulation of DRE genes associated with the autophagolysosomal pathway such as Rab27a (Rab27a:chr9:73097111) was found in both IBP and viral infections in the current study." (PMID 37081881, 2023). "To test whether the structural glycoproteins are sufficient viral factors for Rab27a interaction, we transiently expressed HA-tagged Gn and Gc (HA-Gn and HA-Gc) in HeLa cells in the absence of viral infection." (PMID 39213446, 2024).
glioblastoma (5 papers, 2022 to 2025). The most malignant astrocytic tumor (WHO grade IV). "In our study, we investigate the impact of GDEs on lipid accumulation and oxidation in DCs by inhibiting GDEs secretion through knocking down the expression of Rab27a using a rat orthotopic glioblastoma model." (PMID 39192971, 2024). "Thus, in Rab27a/b double knock out (Rab27-dKO) mice, the brain vasculature is abnormally scarce, while the blood vessels become dysmorphic and hyperpermeable in the context of brain tumors, including syngeneic glioblastoma." (PMID 40408475, 2025). "In this study, shRNAs targeting RAB27A were used in colorectal (CRC) and glioblastoma (GB) cell lines in order to alter EVs secretion." (PMID 35216426, 2022).
non-small cell lung carcinoma (5 papers, 2017 to 2024). A group of at least three distinct histological types of lung cancer, including non-small cell squamous cell carcinoma, adenocarcinoma, and large cell carcinoma. "Research on non-small cell lung cancer (NSCLC) has shown that exosomes produced from tumor cells overexpressing Rab27a can promote DC maturation by upregulating MHC II and the CD80 and CD86 costimulatory markers." (PMID 39062506, 2024). "Overexpression of Rab27a in the non-small-cell lung cancer cell line A549 prompted antitumor immunity, by upregulating the major histocompatibility complex II molecules and promoting the expression of antitumor type I cytokines." (PMID 36986603, 2023). "But the role of Rab27a in non-small cell lung cancer and its possible mechanism is particularly unclear." (PMID 29212243, 2017). "Elevated expression of Rab27a is closely connected with many human cancers containing non-small cell lung cancer (NSCLC)." (PMID 29212243, 2017).
renal fibrosis (5 papers, 2021 to 2026). A final common manifestation of a wide variety of chronic kidney diseases characterized by glomerulosclerosis and tubulointerstitial fibrosis. "Reduction of EVs secretion via pharmacological inhibition or depletion of Rab27a is sufficient to attenuate renal fibrosis." (PMID 37357686, 2023). "Meanwhile, Masson staining, Col-I immunohistochemical staining and fibronectin immunofluorescence staining confirmed that Rab27a knockout ameliorated renal fibrosis after UUO by inhibiting collagen and fibronectin deposition." (PMID 34522205, 2021). "Western blotting confirmed that knockout of Rab27a ameliorated renal fibrosis after UIRI by inhibiting fibroblast activation (α-SMA) and fibronectin deposition." (PMID 34671216, 2021). "The inhibition of exosome secretion by Rab27a knockout or GW4869 treatment ameliorates renal fibrosis following UIRI in vivo." (PMID 34671216, 2021). "We next constructed Rab27a knockout mice to further confirm the role of exosome-mediated epithelial-fibroblast communication relevant to renal fibrosis in UUO mice." (PMID 34522205, 2021). "Taken together, blockade of exosome secretion either by knockdown of Rab27a or DMA promotes renal fibroblasts apoptosis, reduces fibroblast population and mitigate renal fibrosis in an established kidney injury." (PMID 37828075, 2023). "In addition, the inhibition of exosome secretion by Rab27a knockout or GW4869 treatment abolished fibroblast activation and ameliorated renal fibrosis." (PMID 34522205, 2021).
albinism (4 papers, 2008 to 2024). A congenital disorder characterized by partial or complete absence of melanin pigment in the eyes, hair, or skin. "Mutations in RAB27A, LYST, and AP3B1 give rise to FHL associated with oculocutaneous albinism, and patients with FHL are usually only screened for mutations in these genes when albinism is observed." (PMID 25312756, 2015). "These variations are caused by mutations in three genes located on the 15q21 region, i.e., MYO5A, RAB27A, and MLPH, giving rise to three distinct clinical forms, respectively, GS1, GS2, and GS3, with albinism as a common feature." (PMID 38993473, 2024).
choroideremia (4 papers, 2013 to 2024). Choroideremia (CHM) is an X-linked chorioretinal dystrophy characterized by progressive degeneration of the choroid, retinal pigment epithelium (RPE) and retina. "Mutations in the Rab escort protein 1 (REP1), which is essential for prenylation of Rab GTPases, disrupt Rab27a trafficking through accumulation of unprenylated Rab27a, causing choroideremia." (PMID 29034219, 2017). "They found that Rab38, Rab27a, Rab27b, and Rab42 are prenylated the slowest and concluded that this finding may implicate them in choroideremia, since they may be more impacted by REP-1 deficiency when only REP-2 is present." (PMID 38920696, 2024). "Rab27a was the first Rab reported to be unprenylated in choroideremia, which has since been validated in multiple reports, including the present study." (PMID 38920696, 2024). "Rab27a, which has been identified in multiple studies as poorly prenylated in choroideremia, was among the nine." (PMID 38920696, 2024). "Our work points to possible contribution of Rab38 to the emergence of choroideremia in addition to Rab27a and Rab27b." (PMID 24358126, 2013). "We obtained a first snapshot of prenylation hierarchy of Rabs, identifying Rabs that are more vulnerable to a general reduction in prenylation capacity than others and in addition to Rab27a might be underprenylated in choroideremia patients." (PMID 24358126, 2013). "Interestingly, Rab27a, which is expressed in the cell layers that degenerate in choroideremia and has been reported to be underprenylated in choroideremia patient cells, displays one of the slowest prenylation rates, which is approximately an order of magnitude slower than that of other Rabs." (PMID 24358126, 2013). "In conclusion, Rab27a is prenylated slowly in vivo and in vitro, but in addition also other Rabs like Rab38 and Rab42 show slow prenylation kinetics and could therefore potentially play a role in choroideremia." (PMID 24358126, 2013). "However, the Rab27a knockout mouse does not appear to have any eye defects, suggesting that other Rabs than Rab27a might also contribute to the loss of vision in choroideremia patients." (PMID 24358126, 2013). "Despite interest in Rab27a in choroideremia, a molecular mechanism linking Rab27a under-prenylation with chorioretinal degeneration has not been elucidated." (PMID 38920696, 2024).
hemophagocytic lymphohistiocytosis (4 papers, 2021 to 2024). "However, there is no such fatal hemophagocytic disorder in Munc13-4-deficient Jinx mice under the SPF condition, as in the case of Rab27a-deficient ashen mice." (PMID 34483204, 2021).
lymph node metastasis (4 papers, 2015 to 2024). "High expression of Rab27A was significantly associated with lymph node metastasis (HR 1.53, 95% CI 1.00–2.34, p = 0.048)." (PMID 32839520, 2020). "The results suggested that high expression of Rab27A was significantly associated with lymph node metastasis (HR 1.53, 95% CI 1.00–2.34, p = 0.048)." (PMID 32839520, 2020). "The IHC data indicated that the Rab27A protein expression in CRC was statistically correlated with lymph node metastasis (p = 0.022) and TNM stage (p = 0.026)." (PMID 26070933, 2015). "Previously, we found that negative RAB27A expression positively correlated with lymph node metastasis and poor prognosis in patients with RCC, as evaluated using tissue microarray samples; RAB27A may affect the metastatic potential of cancer cells." (PMID 38685086, 2024).
Alzheimer disease (3 papers, 2019 to 2020). A progressive, neurodegenerative disease characterized by loss of function and death of nerve cells in several areas of the brain leading to loss of cognitive function such as memory and language. "It important to note that upregulation of the RAB27A protein in basal forebrain neurons has been associated with mild cognitive impairment and Alzheimer disease." (PMID 31323913, 2019). "Upregulation of RAB27A protein in basal forebrain neurons has been associated with mild cognitive impairment and Alzheimer’s disease." (PMID 31323913, 2019).